CACNA1A (calcium voltage-gated channel subunit alpha1 A)
Diseases named in the same sentence as CACNA1A in open-access papers (continued):
Sharing a sentence is not in itself a finding about the gene and the disease.
migraine (continued). "Notwithstanding, even in migraine with aura patients, not suffering from familial hemiplegic migraine and not having any kind of genetic defect involving CACNA1A, a dysfunction of calcium channels has been described, suggesting that this is a more generalized problem among patients with migraine." (PMID 28082766, 2016). "Molecular analysis of the CACNA1A and ATP1A2 genes in patients with migraine without aura and with aura, has shown that these two genes are not involved in common forms of migraine, although similar studies have not examined the SCN1A gene." (PMID 21713554, 2011). "Acetazolamide has been used in CACNA1A patients to prevent FHM, and a recently designed non-commercial clinical trial using acetazolamide in PMM2-CDG to improve cerebellar syndrome also showed improvement in a treated patient who suffered from almost weekly SLE episodes together with migraine." (PMID 34708008, 2021).
familial hemiplegic migraine (100 papers, 2005 to 2025). A migraine disorder characterized by individual and family history of aura that includes motor weakness. "Genetic studies have identified several mutations associated with familial hemiplegic migraine, including CACNA1A (FHM1), ATP1A2 (FHM2), and SCN1A (FHM3)." (PMID 41552155, 2025). "CACNA1A encodes the alpha-1a subunit of the voltage-dependent P/Q calcium channel, and has been linked repeatedly to familial hemiplegic migraine (FHM), a subtype of MA." (PMID 38731230, 2024). "Pathogenic variants in the CACNA1A gene have been linked to various neurological disorders, including familial hemiplegic migraine and cerebellar conditions." (PMID 38785745, 2024). "Specifically, variants in CACNA1A have been linked to familial hemiplegic migraine and epileptic seizures, underscoring its importance in neurological disease etiology." (PMID 38785745, 2024). "These channels give rise to P/Q-type calcium currents and its encoding gene, CACNA1A, stands as a classical genetic locus associated with the rare genetic disease familial hemiplegic migraine (FHM)." (PMID 37370051, 2023). "Of these variants, CACNA1A is a well-known gene linked to familial hemiplegic migraine, a rare subform of MA58,59." (PMID 35115687, 2022). "CACNA1A pathogenic variants have been linked to several neurological disorders including familial hemiplegic migraine and cerebellar conditions." (PMID 33557884, 2021). "The calcium channel gene, CACNA1A, has been identified as a key gene in which mutations can cause familial hemiplegic migraine (FHM), along with several other FHM-related ion channel genes (ATP1A2, SCN1A)." (PMID 32233732, 2020). "Mutations in ion channel genes, in particular CACNA1A, have been implicated in familial hemiplegic migraine (FHM) and in the development of concussion-related symptoms in response to trivial head trauma." (PMID 32233732, 2020). "The most established molecular knowledge of migraine comes from mutations in the three genes for familial hemiplegic migraine (FHM) – CACNA1A, ATP1A2 and SCN1A." (PMID 23675283, 2013). "Familial hemiplegic migraine (FHM) type 1 is a rare monogenic dominant autosomal disease due to CACNA1A gene mutations." (PMID 22527033, 2012). "Both conditions share potential genetic underpinnings, with genes associated with familial hemiplegic migraine (such as CACNA1A, ATP1A2, and SCN1A) implicated in certain aura subtypes, though evidence for genetic influences is more robust in MA due to larger-scale studies." (PMID 40873917, 2025). "The CACNA1A gene encodes the pore-forming subunit of the Cav2.1 (P/Q type) neuronal calcium channel and pathogenic variants cause a variety of neurological disorders including episodic and congenital ataxia, familial hemiplegic migraine, developmental delay and epilepsy." (PMID 40703772, 2025). "The CACNA1A gene has been implicated in rare forms of Familial Hemiplegic Migraine (FHM)." (PMID 40869402, 2025). "HM is categorised based on family history, with familial hemiplegic migraine (FHM) linked to pathogenic variants in the CACNA1A, ATP1A2, and SCN1A ion transport genes." (PMID 40725463, 2025). "Familial hemiplegic migraine (FHM) is a severe neurogenetic disorder for which three causal genes, CACNA1A, SCN1A, and ATP1A2, have been implicated." (PMID 35928792, 2022). "Familial hemiplegic migraine (FHM), which is a subtype of migraine with aura, is caused by mutations in CACNA1A, ATP1A2, and SCN1A." (PMID 33193064, 2020). "Familial hemiplegic migraine (FHM) is due to mutations in the CACNA1A gene, coding for the voltage-gated Cav2.1 calcium channel α subunit." (PMID 25339937, 2014). "Familial hemiplegic migraine (FHM) is an inherited form linked to genetic variants, primarily in the CACNA1A gene." (PMID 40111503, 2025).
familial hemiplegic migraine (continued). "The genetic basis for CSD is supported by its strong association with familial hemiplegic migraine (FHM), where mutations in genes, such as CACNA1A, ATP1A2, and SCN1A, alter ion channel function, predisposing the brain to hyperexcitability." (PMID 40869402, 2025). "Genetic factors play a significant role, with mutations in genes like CACNA1A, ATP1A2, and SCN1A implicated in familial hemiplegic migraine, a rare subtype, and potentially contributing to broader aura susceptibility through ion channel dysfunction." (PMID 40873917, 2025). "The role of the CACNA1A gene in cluster headache was also explored due to its involvement in familial hemiplegic migraine and other neurological disorders." (PMID 39560176, 2025). "Familial hemiplegic migraine (FHM), an autosomal dominant hereditary form of HM, is linked to mutations in specific genes (CACNA1A, ATP1A2, SCN1A) that encode ion channels and transporters critical for neuronal excitability and synaptic transmission." (PMID 40264646, 2025). "Genetic studies have identified several ion channel genes, including CACNA1A, ATP1A2, and SCN1A, which encode ion channels and transport proteins, as possible causes or contributors to familial hemiplegic migraine (FHM)." (PMID 38068897, 2023). "The transmission of three genes linked to ion transport, CACNA1A, ATP1A2, and SCN1A, is responsible for the onset of familial hemiplegic migraine." (PMID 35328439, 2022). "Mutations in the ion transport genes CACNA1A, ATP1A2 and SCN1A can lead to familial hemiplegic migraine, indicating genetic heterogeneity." (PMID 34384358, 2021). "Familial hemiplegic migraine (FHM) is a monogenic autosomal dominant subtype of migraine with aura, which is caused by mutations in three genes, which are CACNA1A, ATP1A2, and SCN1A." (PMID 35281991, 2021). "CACNA1B is a member of a family of genes, which includes CACNA1A, that has been linked to a monogenic subtype of MTA, namely familial hemiplegic migraine (FHM)." (PMID 32968778, 2020). "Stroke-like episodes (SLE) occur in phosphomannomutase deficiency (PMM2-CDG), and may complicate the course of channelopathies related to Familial Hemiplegic Migraine (FHM) caused by mutations in CACNA1A (encoding CaV2.1 channel)." (PMID 29470411, 2018). "Heritability seems to be more eminent in MwA subtype than MwoA, further supported by the identification of mutations in three ion transporter genes (CACNA1A, ATP1A2, and SCN1A) associated with familial hemiplegic migraine (FHM); a rare monogenic form of MwA." (PMID 36698892, 2022). "This is the case of PMM2-CDG and some channelopathies related to CACNA1A, ATP1A2, and SCN1A mutations, leading to episodes called familial hemiplegic migraine (FHM)." (PMID 34708008, 2021). "Familial hemiplegic migraine (FHM) is an autosomal dominant disorder, classified into 3 subtypes, based on the gene involved (CACNA1A in FHM1, ATP1A2 in FHM2 and SCN1A in FHM3)." (PMID 34320921, 2021). "In addition, 3 heterozygous missense mutations in other genes within the panel were identified (CACNA1A—p.Asp1723Asn and p.Ala987Ser; ATP1A2—p.Glu219Gln) suggesting that these patients have familial hemiplegic migraine (FHM) which has symptomatic features which overlap with CADASIL." (PMID 31915071, 2020). "Mutations in CACNA1A, ATP1A2 and SCN1A genes have been associated with familial hemiplegic migraine (FHM), a rare monogenic form of migraine." (PMID 23566281, 2013). "Mutations in three genes encoding neural ion channels, CACNA1A, ATP1A2, and SCN1A, have been described in patients with familial hemiplegic migraine (FHM), a rare monogenic, autosomal dominant form of migraine with aura." (PMID 21344296, 2011). "On the other hand, mutations in the four genes (CACNA-1A, ATP1A2, SCN1A, and PRRT2) identified in patients with familial hemiplegic migraine (FHM) are associated with a reduced threshold value of cortical spreading depression, which is also responsible for auras." (PMID 37048668, 2023).
familial hemiplegic migraine (continued). "An Italian family with familial hemiplegic migraine (FHM) with the absence of mutations in the known genes associated with this disorder, namely ATP1A2, ATP1A3, CACNA1A, and SCN1A, has recently been reported." (PMID 32549268, 2020). "Previous hypotheses of molecular mechanisms in migraine have come from familial hemiplegic migraine (FHM), a rare Mendelian form of the disease, where three ion channel genes are known to be involved (CACNA1A, ATP1A2, and SCN1A)." (PMID 27543003, 2016). "Indeed, one might reasonably screen the other familial hemiplegic migraine genes FHM2 (ATP1A2), FHM3 (SCN1A) along with FHM1 (CACNA1A) in case these are responsible for EA2‐like symptoms in a patient." (PMID 27066515, 2016).
epilepsy (97 papers, 2007 to 2026). A brain disorder characterized by episodes of abnormally increased neuronal discharge resulting in transient episodes of sensory or motor neurological dysfunction, or psychic dysfunction. "Although epilepsy has been reported in patients with both gain-of-function variants and loss-of-function CACNA1A variants, status epilepticus was more frequently associated with gain-of-function variants." (PMID 40703772, 2025). "This study identified a significant association between the CACNA1A rs16023 variant and both DD/ID and epilepsy comorbidity in Korean pediatric patients." (PMID 40725423, 2025). "Heterozygous CACNA1A loss-of-function pathogenic variants are rarely associated with epilepsy or epileptic encephalopathy." (PMID 39416668, 2024). "What they found was that five of the eight persons having a mutation in the CACNA1A gene suffered from epilepsy and FHM together, whereas one patient suffered from epilepsy only." (PMID 38273253, 2024). "In cases of epilepsy in children associated with the CACNA1A variant, focal seizures predominantly occurred, possibly followed by unilateral brain atrophy." (PMID 38785745, 2024). "CACNA1A mutations have been implicated in both pure epilepsy and a spectrum of epilepsy phenotypes based on the molecular sub-region of the mutations." (PMID 39161505, 2024). "Genotype–phenotype correlations in our patients and in previously reported biallelic CACNA1A variants in epilepsy patients." (PMID 39416668, 2024). "The correlation between the CACNA1A genetic variants and the occurrence of epilepsy seems to have been well documented for quite a long time." (PMID 38785745, 2024). "Genome association studies have discovered epilepsy disease susceptibility to variations in the CACNA1A gene." (PMID 37239364, 2023). "Recent advances in NGS have revealed that de novo missense mutations in the CACNA1A gene contribute to ID/DD and therapy-resistant epilepsy." (PMID 37152436, 2023). "A total of 33 children underwent preoperative genetic whole‐exome testing, and 4 of them had pathogenic genes related to epilepsy, including CACNA1A, CREBBP, MTOR, and NPRL2." (PMID 37786975, 2023). "Epilepsy has been associated with mutations in the human gene orthologs of cac (CACNA1A/B/E), alpha-Spec (SPTAN1) and slo (KCNMA1)." (PMID 37759179, 2023). "Another gene strongly associated with epilepsy is CACNA1A, for which we have found three different variants in three different patients (AUT117, AUT161, who also has an intellectual disability, and AUT221)." (PMID 38003033, 2023). "CACNA1A variants are related to a wide range of neurodevelopmental disorder phenotypes including epilepsy, GDD/ID, and ASD." (PMID 37555011, 2023). "In summary, we identified CACNA1A mutations in ten unrelated cases with relatively mild and pure epilepsy." (PMID 35600082, 2022). "Biallelic variants in CACNA1A have previously been reported in nine individuals (four families) presenting with epilepsy and cognitive impairments of variable severity and age-of-onset." (PMID 36063114, 2022). "CACNA1A mutations have also been occasionally identified in patients with mild form of epilepsy, including absence epilepsy, juvenile myoclonic epilepsy, and idiopathic epilepsy." (PMID 35600082, 2022). "In the present study, we identified 12 CACNA1A mutations in ten cases of mild form of epilepsy, including four de novo null mutations, four de novo missense mutations, and two pairs of compound heterozygous missense mutations." (PMID 35600082, 2022). "Several case reports described epilepsy as a part of the clinical manifestation of disease in patients with CACNA1A mutations that can be the only symptom or can appear along with the other signs." (PMID 34727962, 2021). "Up to now, some pathogenic variants in CACNA1A have been reported, which are in association with stroke and epilepsy." (PMID 34727962, 2021).
epilepsy (continued). "Though, most of the evidence of an association between CACNA1A disorders and epilepsy originated from small case series." (PMID 33544220, 2021). "Established manifestations of CACNA1A variants comprehend neuropsychiatric disorders, paroxysmal dystonia, epilepsy, as well as complex phenotypes characterized by a various combination of early developmental delay and epileptic encephalopathy." (PMID 33737904, 2021). "This notion is supported by previous studies showing that CACNA1G (Cav3.1) and CACNA1A (Cav2.1) are genetic modifiers of epilepsy associated with Dravet syndrome." (PMID 34399820, 2021). "Focusing on moderate-impact “high-quality variants”, we also identified mutations in GASH/Sal genes that were previously reported as polymorphisms associated with epilepsy, such as Cacna1a, Cacna2d3, Grik1 and Jup." (PMID 32168507, 2020). "We describe a four‐year‐old female with recurrent ischemic strokes beginning at six weeks of age, intractable epilepsy, and significant global developmental delay, who was found to have a novel de novo likely pathogenic p.Leu1692Gln variant in CACNA1A." (PMID 32692472, 2020). "Further, seizures, epilepsy, and epileptic encephalopathy all have been described as part of the phenotypic spectrum of CACNA1A mutations." (PMID 32692472, 2020). "A potential association of epilepsy with CACNA1A mutations has been reported in EA2 patients, similar to the phenotype described for episodic ataxia type 1." (PMID 32471306, 2020). "More recently, CACNA1A mutations have been described in individuals diagnosed with ID, epilepsy, ADHD and/or ASD." (PMID 28713243, 2017). "Prior studies have also suggested that CACNA1A 3′ UTR polymorphisms may modulate susceptibility to epilepsy and neurodevelopmental disorders." (PMID 40725423, 2025). "On the contrary, data regarding epilepsy is poor and the precise prevalence of epilepsy in individuals with CACNA1A mutation is unknown." (PMID 38273253, 2024). "However, a recently performed multicentric study found that individuals with CACNA1A-associated epilepsy mostly suffer from permanent cerebellar dysfunction and early moderate to severe global development delay and intellectual deficiency." (PMID 38273253, 2024). "CACNA1A is a well-known epilepsy-associated gene (OMIM*601011)." (PMID 37152436, 2023). "This study suggested that CACNA1A gene is potentially associated with epilepsy." (PMID 35600082, 2022). "These CACNA1A-associated disorders are frequently accompanied with cognitive impairments, which are particularly recognized as devastating co-morbidities of epilepsy and other neuronal disorders." (PMID 35548926, 2022). "In the present study, we identified CACNA1A mutations in the cases with relatively mild epilepsies." (PMID 35600082, 2022). "Thus, tg mice are a useful animal model for studying the cognitive co-morbidities of CACNA1A-associated disorders, and epilepsy in particular." (PMID 35548926, 2022). "This study suggested that CACNA1A mutations were potentially associated with pure epilepsy and the spectrum of epileptic phenotypes potentially ranged from the mild form of epilepsies such as absence epilepsy or partial epilepsy, to the severe form of developmental epileptic encephalopathy." (PMID 35600082, 2022). "However, as point mutations are also associated with episodic ataxia 2, which sometimes is presented with epilepsy, these models would help to learn more about molecular mechanisms that cause loss of function of CACNA1A gene." (PMID 33671313, 2021). "Interestingly, in double‐mutant mice carrying the epilepsy‐causing Kcna1–/– mutation in addition to another epileptogenic mutation in the P/Q‐type calcium channel gene Cacna1a (Cacna1atottering), epilepsy was mutually suppressed." (PMID 33484493, 2021).